TAL1 (TAL bHLH transcription factor 1, erythroid differentiation factor)
Diseases named in the same sentence as TAL1 in open-access papers (continued):
Sharing a sentence is not in itself a finding about the gene and the disease.
T-cell leukemia (13 papers, 2008 to 2025). A malignant disease of the T-lymphocytes in the bone marrow, thymus, and/or blood. "The potential TAL1 protein targets associated with the implementationof its transcriptional activity are considered as promising targets for the therapy ofTAL1-associated T-cellleukemia.These proteins include UTX demethylase (also known as KDM6A)." (PMID 29713515, 2018). "Increased level of TAL1 leads to hypersensitivity to erythropoietin, resulting in excessive erythrocytosis, and is the most common molecular abnormality found in human T-cell leukemia." (PMID 40149853, 2025). "The SCL/TAL1 Interrupting Locus (STIL) gene is associated with the development of stem cell and T-cell leukemia." (PMID 37834064, 2023). "It has been determined that the use ofHDAC histone deacetylase inhibitors leads to a decreasein TAL1 expression and induces the apoptosis of blast cells of T-cellleukemia." (PMID 29713515, 2018). "It is very interesting that the TAL1 promoter-IV is specifically active in human T-cell leukemia." (PMID 32086528, 2020). "This negative impact of TAL1 on E47 homodimer formation is implicated in cases of T-cell leukemia, where TAL1 is aberrantly expressed." (PMID 33293632, 2020). "In humans, activation of the TF TAL1, normally expressed early in the erythroid lineage, has been shown to alter a core transcriptional regulatory circuit that in turn leads to tumor onset (T cell leukemia)." (PMID 29560857, 2018). "Overall, our study supports previous researches indicating GSKJ4 as a promising therapeutic agent in Notch1- and TAL1- dependent T-ALL, while laying the basis for extending its potential use also to Notch3- and c-Myc- dependent T-cell leukemia contexts." (PMID 31001470, 2019). "This deletion has been detected in20–25% of patients with T-ALL.However, in most TAL1-positive cases of T-cell leukemia, an abnormally high expressionof TAL1 is effected without the participation of chromosomalrearrangements." (PMID 29713515, 2018).
stem cell leukemia (11 papers, 2012 to 2024). "To investigate whether the fusion proteins target a common transcription factor network we performed motif enrichment analysis on their binding sites, using weight matrices of AML1/RUNX1, C/EBPA, the ETS factor SPI1, GATA and TAL1, all transcription factors reported to be mutated in acute leukemias." (PMID 28030795, 2017). "The TAL1 gene is more commonly known as SCL/TAL1 (stem cell leukaemia/T‐cell acute lymphoblastic leukaemia) and it is an essential TF in normal and malignant hematopoiesis, (i.e. the production of blood cells) (Porcher, Chagraoui, & Kristiansen, 2017)." (PMID 32432381, 2020). "Among many others, p27, c-Myc, E47, and Tal1/Scl (T cell acute leukemia 1/stem cell leukemia) are well known substrates of SCFSkp2." (PMID 24868554, 2014). "TAL1 (T cell acute lymphocytic leukaemia 1), also known as SCL (stem cell leukaemia), is a critical haematopoietic regulator that plays a key role in both embryonic and adult HSC specification and its rearrangement is associated with several human leukaemias (Lécuyer & Hoang, 2004)." (PMID 26996518, 2016).
breast carcinoma (9 papers, 2009 to 2024). "Among the candidate CpGDMs, we found eight genes with differential methylation previously associated with breast cancer susceptibility and pathology in the G2SBC and COSMIC Databases (AMOTL1, CDCP1, CYFIP1, MAP3K6, MIB2, SDK1, TAL1, and TYROBP)." (PMID 33145876, 2021). "In breast cancer, eight winning TFs (ZBTB16, KLF2, KLF4, NR2F1, EGR1, FOSB, EPAS1, and GPRASP1) can form a coregulatory network, and three other winning TFs (MYBL2, FOXM1, and TAL1) can form another coregulatory network." (PMID 36101460, 2022).
lymphoma (7 papers, 2012 to 2023). A malignant (clonal) proliferation of B- lymphocytes or T- lymphocytes which involves the lymph nodes, bone marrow and/or extranodal sites. "Transgenic mice where a TAL1 DNA binding mutant is expressed still develop T cell leukemia/lymphoma." (PMID 24847444, 2014). "Lck promoter driven TAL1 transgenic mice also develop lymphomas of a predominantly mixed T and B cell phenotype." (PMID 24847444, 2014).
glioma (6 papers, 2019 to 2024). A benign or malignant brain and spinal cord tumor that arises from glial cells (astrocytes, oligodendrocytes, ependymal cells). "The direct target of mir‐425‐5p is TAL1, which exhibits a carcinogenic role in glioma cells and can activate the MIR17HG promoter, leading to an upregulation of its expression through a positive feedback loop." (PMID 38321787, 2024). "In this study, we examined the expression and functions of SLUG and TAL1 transcription factors, in gliomas." (PMID 34771555, 2021). "To date, the expression, regulation, and contribution of SLUG and TAL1 transcription factors during gliomagenesis have been poorly documented, especially using current models for gliomas that maximize relevance to this pathology." (PMID 34771555, 2021). "Similar to SLUG, the expression of TAL1 is thus complex in gliomas, combining the expression of several isoforms in few glioma cells and in the tumor microenvironment." (PMID 34771555, 2021). "In the present study, we profiled the expressions of FXR1, MIR17HG, miR-346, miR-425-5p and TAL1 in glioma tissues and cells." (PMID 30691465, 2019). "we investigated the expression of FXR1, MIR17HG, miR-346, miR-425-5p, TAL1 and DEC1 in glioma cells and elucidated the underlying molecular mechanisms in glioma cells." (PMID 30691465, 2019). "TAL1 knockdown facilitated inhibition of glioma cell malignant behavior, indicating that TAL1 functions as an oncogene in glioma cells." (PMID 30691465, 2019). "MIR17HG serves as ceRNA against miR-346/miR-425-5p to up-regulate TAL1 in glioma cells." (PMID 34420031, 2021). "Further, we investigated the effect of TAL1 on glioma cells." (PMID 30691465, 2019). "TAL1 was a direct target of miR-346/miR-425-5p, and played oncogenic role in glioma cells." (PMID 30691465, 2019). "Our results showed that TAL1 expression was raised in glioma tissues and cells." (PMID 30691465, 2019). "We first detected the expression of TAL1 in glioma tissues and cells." (PMID 30691465, 2019). "Moreover, overexpression of miR-346/miR-425-5p and TAL1 simultaneously reversed the effect of overexpression of miR-346/miR-425-5p or TAL1 on DEC1 expression, suggesting DEC1 was involved in miR-346(miR-425-5p)/TAL1-mediated regulation of glioma cells." (PMID 30691465, 2019). "In particular, the reactivation or overexpression of developmental transcription factor genes has been repeatedly implicated in a variety of tumors, including TAL1 (SCL) and RUNX1 in leukemia, SOX10 and MITF in melanoma and GLI1 in glioma." (PMID 31221659, 2019). "In addition, in the pre-miR-346 + TAL1 group, TAL1 rescued the inhibitory effect of pre-miR-346 + TAL1-NC on the proliferation, migration and invasion of glioma cells." (PMID 30691465, 2019). "Likewise, TAL1 mRNA and protein expression was robustly upregulated in glioma U87 and U251 cells." (PMID 30691465, 2019). "Western blot were used to explore the expression of FXR1, TAL1 and DEC1 in glioma tissues and cells." (PMID 30691465, 2019). "FXR1/MIR17HG/miR-346(miR-425-5p)/TAL1/DEC1 axis plays a novel role in regulating the malignant behavior of glioma cells, which may be a new potential therapeutic strategy for glioma therapy." (PMID 30691465, 2019). "Mechanistically, we could not detect an influence of TAL1 and SLUG on the two key glioma transcription factors we explored (OLIG2 and SOX2) so their specific downstream targets remain to be fully identified." (PMID 34771555, 2021).
lung carcinoma (6 papers, 2016 to 2025). "Our results show that TAL1 is a lung-specific gene associated with lung carcinoma and directly regulates TGFBR2, which was previously annotated as a tumor suppressor gene." (PMID 36902378, 2023). "In 2022, a study on lung cancer cells indicated that hypoxia‐inducible factor 1α (HIF1α) binds to the promoter region of SCL/TAL1 interrupting locus (STIL), activating its expression." (PMID 40377005, 2025). "The KM plot analysis showed that the overregulation of three oncogenes (SOX4, BZW2, and FOXM1) as well the downregulation of four tumor suppressors (SOX17, ZBTB16, TAL1, and KLF4) is associated with worse overall survival (OS) for lung cancer patients." (PMID 36661515, 2023). "Another research also proves that in lung cancer patients, downregulation of TAL1 is negatively related to OS, suggesting TAL1's suppressing function in lung cancer, despite TAL1 is considered to be an oncogene in some diseases." (PMID 37826914, 2023). "The seven top deregulated transcription factors (SOX4, SOX17, BZW2, FOXM1, ZBTB16, TAL1, and KLF4) consistently appear to be co-expressed with other frequent DEGs and transcription factors throughout the analysis in lung cancer and PAH." (PMID 36661515, 2023). "Two of the most frequently dysregulated transcription factors are co-expressed in lung cancer and PAH (FOXM1 and FOXF1), while the other six frequently deregulated transcription factors are co-expressed only in lung cancer (TCF21, SOX17, TAL1, LMO2, KLF2, and TBX4)." (PMID 36661515, 2023). "Moreover, FOXF1 is also co-expressed in the CCP of the LC RNA-Seq datasets, along with seven of the most frequently dysregulated TFs (FOXM1, SOX17, TAL1, TCF21, TBX4, LMO2, and KLF2), suggesting its importance as a regulator of gene expression during lung cancer progression." (PMID 36661515, 2023).
anemia (5 papers, 2009 to 2024). A reduction in the number of red blood cells, the amount of hemoglobin, and/or the volume of packed red blood cells. "Tal1 (SCL) is a DNA-binding transcription factor that plays a key role in hematopoiesis, with mouse embryos that carry a double knockout of Tal1 dying around embryonic day E9.5 from severe anemia." (PMID 39026254, 2024). "The pivotal role of TAL1 had previously been demonstrated in hematopoiesis; in those experiments, Tal1(−/−) global knockout mouse embryos died with severe anemia around GD5.0." (PMID 31521203, 2019). "The knockout of Tal1 in adult mice results in anaemia, with a defect in late erythroid maturation." (PMID 30653565, 2019). "The transcription factors Tal1, Gata1, Lmo2 and Fog1 (Zfpm1) all had lower expression in C57BL/6 than BALB/c consistent with more severe anaemia in C57BL/6." (PMID 19365556, 2009). "Several transcription factors regulating haematopoiesis, Tal1, Gata1, Zfpm1 and Klf1 were expressed at consistently lower levels in C57BL/6 mice suggesting that these mice have a lower haematopoietic capacity and therefore less ability to recover from haemolysis induced anaemia after infection." (PMID 19365556, 2009).
melanoma (4 papers, 2015 to 2023). A malignant, usually aggressive tumor composed of atypical, neoplastic melanocytes. "We validated μ-cisTarget by re-analyzing the TAL1 and LMO1 enhancer mutations in T-ALL, and the TERT promoter mutation in melanoma." (PMID 28854983, 2017). "For melanoma samples without TERT promoter mutation, we predicted HMGA2, HIF1, RUNX2 and TAL1 as the most significant regulators." (PMID 31888467, 2019).
chronic myeloid leukemia (3 papers, 2021 to 2023). "In addition, using the chronic myeloid leukemia (CML) cell line K562 we showed that TAL1-short promotes erythropoiesis." (PMID 37379322, 2023). "Enhancer transcription at this location was absent in the chronic myelogenous leukemia cell line K562, which was consistent with lower transcription of TAL1 compared with Jurkat cells." (PMID 33502116, 2021).
Obesity (3 papers, 2022 to 2024). Accumulation of substantial excess body fat. "Rest plays a crucial role in preventing senescence phenotypes, while Tal1 is implicated in high risk of obesity." (PMID 38826189, 2024). "Genetically, TAL1 rs2984618 and a mutation in the CART gene were found to be associated with both obesity and depression, along with the relationship being partially mediated by some FTO variants." (PMID 35308733, 2022).
bladder cancer (2 papers, 2023 to 2024). "A 5-gene panel (VAX1, CFTR, KCNV1, PROX1, and TAL1) had an 88.7% sensitivity and an 87.3% specificity for the diagnosis of bladder cancer." (PMID 37627900, 2023). "The methylation frequency of eight genes (VAX1, ECEL1, KCNV1, LMX1A, PROX1, SLC6A20, TAL1, and TMEM26) was significantly higher in the urine of bladder cancer patients as compared to that of normal controls." (PMID 37627900, 2023).
glioblastoma (2 papers, 2021 to 2023). The most malignant astrocytic tumor (WHO grade IV). "Next, we asked whether this differential expression of apoptotic genes by the isoforms will result in differential cell growth as suggested by research demonstrating that high amounts of TAL1-short in glioblastoma reduced growth." (PMID 37379322, 2023). "By using the RNA seq database from the Human Glioblastoma Cell Culture resource, SLUG (SNAI2) was significantly more expressed in GSC cultures with a mesenchymal phenotype, while TAL1 expression was not specific to any subtype." (PMID 34771555, 2021).
lung adenocarcinoma (2 papers, 2017 to 2022). A carcinoma that arises from the lung and is characterized by the presence of malignant glandular epithelial cells. "TAL1 is a hub node of a transcriptional regulatory network in lung adenocarcinoma, promoting the TGF-β signaling pathway." (PMID 36101460, 2022). "Especially, we found three genes (SPARCL1, ENG and TAL1) harboring frequently hypermethylated CpG sites within their promoters were also frequently down-regulated in lung adenocarcinoma." (PMID 28178989, 2017). "Thus, SPARCL1 and TAL1 might also be important tumor suppressors of lung adenocarcinoma and it would be interesting to study whether their silencing could be reactivated by demethylation and whether the reactivation could suppress cancer cells." (PMID 28178989, 2017). "Accordingly, we found five genes (HOXA9, TAL1, ATP8A2, ENG and SPARCL1) corresponding to the five CpG sites had above 90% hypermethylation frequencies in the 539 lung adenocarcinoma samples from TCGA." (PMID 28178989, 2017). "Gene expression analysis revealed that four of the five genes, HOXA9, TAL1, ATP8A2, ENG and SPARCL1, each harboring one of the five frequently hypermethylated CpG sites within its promoters, were also frequently down-regulated in lung adenocarcinoma." (PMID 28178989, 2017).
T cell lymphoma (2 papers, 2009 to 2012). "Transgenic expression of the p22 form of Tal1 also causes T cell lymphoma in mice." (PMID 19688092, 2009). "Therefore, we made use of our collection of T cell lymphomas developed in transgenic mice expressing Id1, which like TAL1, inhibits E protein function." (PMID 22393458, 2012).
atherosclerosis (1 paper, 2025). A disease characterized by the build-up of fatty material and calcium deposition in the arterial wall resulting in partial or complete occlusion of the arterial lumen. "Taken together, these findings demonstrated the protective role of TAL1 in endothelial cells against atherosclerosis." (PMID 40598260, 2025). "In vivo findings exposed that endothelial-specific overexpression of TAL1 in ApoE–/– mice significantly impeded the aortic plaque formation, indicating the role of TAL1 in endothelial cells against atherosclerosis." (PMID 40598260, 2025). "Remdesivir impedes atherosclerosis progression by re-establishing the interaction between TAL1 and TRAF6, diminishing endothelial activation." (PMID 40598260, 2025). "Whether remdesivir could ameliorate atherosclerosis through TRAF6 ubiquitination regulated by TAL1 remains unclear." (PMID 40598260, 2025). "Finally, over-expression TAL1 specifically in endothelial cells decreased inflammatory response and progression of atherosclerosis in ApoE-/- mice fed with western diet." (PMID 40598260, 2025). "We investigated whether TAL1 over-expression could decrease atherosclerosis in vivo." (PMID 40598260, 2025).
behavioral disorder (1 paper, 2020). "Our studies suggest Tal1 dependent anterior brainstem GABAergic and glutamatergic neuron subgroups as an important new focus for understanding the neurobiology of this common behavioral disorder." (PMID 33087695, 2020).
cerebellar hemangioblastoma (1 paper, 2023). A histologically benign tumor, usually cystic with a vascular mural nodule, that is most often found in the cerebellum though it has been reported at other sites within the neuraxis. "Ranking for amount of TAL1 staining was as follows: cerebellar hemangioblastomas, clear cell renal cell carcinomas, spinal hemangioblastomas, extra-adrenal paragangliomas, pancreatic neuroendocrine tumors, and pheochromocytomas." (PMID 37174017, 2023). "Cytoplasmic TAL1 staining was observed in all VHL tumors and was strongest in extra-adrenal paragangliomas, cerebellar hemangioblastomas, and spinal hemangioblastomas." (PMID 37174017, 2023).
cervical cancer (1 paper, 2013). A primary or metastatic malignant neoplasm involving the cervix. "However, the expression of transcription factors for erythropoiesis, including GATA-1, KLF1, and SCL/TAL1, was not changed significantly in cervical cancer tissues compared to the controls (data not shown)." (PMID 23349856, 2013).
COVID-19 (1 paper, 2021). A disease caused by infection with severe acute respiratory syndrome coronavirus 2. "We prioritized 4 out of 5 microglia PFC TFs (IRF8, ATF5, SPI1, TAL1) based on the upregulation in their activity in patients with COVID-19 (Z > 2.5, P < 0.05 and FDR within cell type < 0.05)." (PMID 34281603, 2021).
Dengue virus infection (1 paper, 2020). "This could potentially affect the availability of free TAL-1 and impede the process of megakaryopoiesis either directly or in combination with other factors, resulting in the decreased platelet numbers seen in the dengue patients." (PMID 33177556, 2020).
erythroleukemia (1 paper, 2020). Acute erythroid leukemia characterised by the presence of at least 50% erythroid precursors and at least 20% myeloblasts in the bone marrow. "To characterize the direct role of −31CBS in chromatin domain organization and TAL1 transcription, we employed CRISPR-Cas9 to delete the core CTCF motif of the −31CBS in the TAL1-expressed erythroleukemia K562 and T-ALL Jurkat cells." (PMID 32086528, 2020).
esophagus cancer (1 paper, 2021). "Activation of the proto-oncogene TAL1 was linked to recurrent deletions of a nearby TAD boundary in T-ALL28, and we identify potential disruptions of this gene in esophagus cancer (translocation causing gain of eQTL and enhancer) and uterus cancer (translocation causing gain of eQTL)." (PMID 34257393, 2021).
glomerulosclerosis (1 paper, 2013). A hardening of the kidney glomerulus caused by scarring of the blood vessels. "Our data suggests that the IAP insertion in Tal1 underlies the histopathological changes in the kidney by three weeks of age, and that glomerulosclerosis is a consequence of an initial developmental defect, progressing in severity over time." (PMID 23301070, 2013).